MC2R (melanocortin 2 receptor)
Diseases named in the same sentence as MC2R in open-access papers (continued):
Sharing a sentence is not in itself a finding about the gene and the disease.
infantile spasms (2 papers, 2015 to 2023). A rare epilepsy syndrome characterized by onset of epileptic spasms in infants between 2 and 12 months of age, and rarely up to 24 months. "In addition, the MC2R rs1893219 A>G variant was associated with better response to glucocorticoid treatment in infantile spasms." (PMID 38348123, 2023).
myelolipoma (2 papers, 2014 to 2024). "Our data indicated that MC2R and/or AR were involved in the pathogenesis of myelolipomas associated with CAH, suggesting a stimulatory hormonal effect as a trigger for tumor growth." (PMID 24884994, 2014). "In conclusion, we first demonstrated here MC2R or AR overexpression in giant bilateral myelolipomas from poor-compliance CAH patients." (PMID 24884994, 2014). "The MC2R gene was overexpressed in the myelolipomas of 3 out of 4 patients." (PMID 24884994, 2014). "Therefore, to our knowledge, our finding is the first evidence of MC2R overexpression in myelolipomas." (PMID 24884994, 2014). "The MC2R gene was overexpressed in myelolipomas from 3 out of 4 patients." (PMID 24884994, 2014). "In this study, we demonstrated that the MC2R gene was overexpressed in 3 out of 4 myelolipomas." (PMID 24884994, 2014). "ACTH likely plays a role in myelolipoma formation; however, we found a decreased expression of the ACTH receptor (MC2R) and androgen receptor (AR) in myelolipoma tissue, and an increased expression in CAH adrenal tissue." (PMID 38473790, 2024). "In this study, we analyzed MC2R and AR expression as well as nCAG AR repeat numbers in two bilateral giant myelolipomas from CAH patients and two unilateral sporadic myelolipomas." (PMID 24884994, 2014). "Despite of chronic ACTH hyperstimulation, myelolipoma from patient 1 did not present MC2R overexpression." (PMID 24884994, 2014). "Indeed, MC2R and androgen receptor (AR) expression was previously evaluated in a single case of giant bilateral myelolipoma in a CAH patient and was negative using a semi-quantitative approach." (PMID 24884994, 2014).
aldosteronomas (1 paper, 2016). "Among the abnormalities in various hormone receptors, an overexpression of the melanocortin type 2 receptor (MC2R) could be responsible for aldosterone hypersecretion in aldosteronomas." (PMID 27445975, 2016).
colitis (1 paper, 2023). Inflammation of the colon. "In addition, the authors observed an improvement in UVB-induced DSS-induced colitis by administering an MC2R inhibitor (which appears to have receptor affinity for ACTH)." (PMID 37508552, 2023).
cryptorchidism (1 paper, 2016). The failure of one or both testes of a male fetus to descend from the abdomen into the scrotum during the late part of pregnancy. "Coincidental hypospadias and unilateral cryptorchidism was found in one boy with disruption of MC2R." (PMID 26523528, 2016).
Cushing syndrome (1 paper, 2017). Cushing's syndrome (CS) encompasses a group of hormonal disorders caused by prolonged and high exposure levels to glucocorticoids that can be of either endogenous (adrenal cortex production) or exogenous (iatrogenic) origin. "Even if these observations suggest that specific MC2R antagonist could help patients with PBMAH, the specific structure of the ACTH produced by PBMAH cells and in ectopic Cushing’s syndrome might raise unexpected difficulties." (PMID 28228747, 2017).
familial tumor syndromes (1 paper, 2026). "PBMAH may also result from alterations in MC2R, PRKACA, and phosphodiesterase (PDE)11A genes, and it can occur as part of familial tumor syndromes such as McCune-Albright syndrome (GNAS), MEN1, familial APC, or hereditary leiomyomatosis and renal cell carcinoma (FH gene variant)." (PMID 41503047, 2026).
Guillain-Barre syndrome (1 paper, 2017). A spectrum of rare post-infectious neuropathies that usually occur in otherwise healthy patients. "α-MSH, which cannot signal through MC2R expressed in the adrenals, inhibits the development of EAE and EAN, a peripheral neuropathy, that serves as a model for some variants of Guillain-Barre Syndrome (GBS)." (PMID 28805746, 2017).
Hyperbilirubinemia (1 paper, 2023). An increased amount of bilirubin in the blood. "We first reported a Chinese family with two affected siblings with a homozygotic variant of c.712C>T/p.H238Y in MC2R, presenting with skin hyperpigmentation, hyperbilirubinemia, and tall stature." (PMID 36909322, 2023).
hyperkalaemia (1 paper, 2009). "Furthermore, MC2R knock out mice have overt aldosterone deficiency and hyperkalaemia despite preservation of a normal zona glomerulosa." (PMID 19170705, 2009).
kidney cancer (1 paper, 2017). Primary or metastatic malignant neoplasm involving the kidney. "Also, five parathyroid hormone-related proteins (PTHrPs) (PTHLH, PTH, HCRT, MC2R, and PTH2) are prominent for three kidney cancers (KICH, KIRC, and KIRP)." (PMID 28676692, 2017).
paraganglioma (1 paper, 2022). A benign or malignant neoplasm arising from paraganglia located along the sympathetic or parasympathetic nerves. "Among the seven down-regulated GPCRs in paraganglioma, Arginine Vasopressin Receptor 1A (AVPR1A), ACTH receptor, MC2R, and PTH1R were the target of 2 to 4 drugs each." (PMID 35203352, 2022).
phaeochromocytoma (1 paper, 2023). "Several ‘APM-associated genes’, including CYP11B2 itself, as well as the ACTH receptor gene MC2R, the neuronal genes NETO2 and BEX1, and TSPAN12, had 2–8-fold lower expression in ZG samples adjacent to an APA than in ZG samples adjacent to a phaeochromocytoma, for example." (PMID 37612380, 2023).
Primary hypothyroidism (1 paper, 2022). A type of hypothyroidism that results from a defect in the thyroid gland. "Another study reported a Caucasian girl with a mutation in MC2R p.S74I, diagnosed with primary hypothyroidism." (PMID 35506146, 2022).
Sepsis (1 paper, 2021). Sepsis is defined as life-threatening organ dysfunction caused by a dysregulated host response to infection. "Adrenal gene expression levels of the ACTH-receptor MC2-R were either increased (p = 0.02 for 3-day sepsis group and p < 0.0001 for 7-day sepsis group), or normal (p = 0.06 for 1-day sepsis group and p = 0.06 for 5-day sepsis group)." (PMID 33593393, 2021).
tumor (4 papers, 2017 to 2026). "IHC was performed on the tumor tissue to detect the expression of LHCGR, MC2R and GPER-1." (PMID 32393232, 2020). "Bilateralism of the tumours, presence of Reinke crystals and expressions of synaptophysin, Inhibin α, CD56, androgen receptor, DLK1, INSL3, CYP11B1, CYP21A2 and MC2R have all been studied as potential markers, but none of these markers individually can reliably discriminate TARTs from LCTs." (PMID 29038332, 2017). "Immunohistochemistry (IHC) showed the tumor tissue that stained positive for luteinizing hormone (LH)/human choriogonadotropin (hCG) receptor (LHCGR), whereas negative for both melanocortin 2 receptor (MC2R) and G protein-coupled receptor-1 (GPER-1)." (PMID 32393232, 2020).
infection (3 papers, 2013 to 2024). The state of being infected such as from the introduction of a foreign agent such as serum, vaccine, antigenic substance or organism. "Since MCR2 immunoreactivity after 14 days pi seems to be mostly localized within cell cytoplasm, it is conceivable that under prolonged stressful conditions like Tc infection, mechanisms about MC2R protein internalization and degradation are boosted, reinforcing MCR2 desensitization." (PMID 31998227, 2019). "The fact that GC rise coincided with the highest circulating amounts of ACTH, together with an intensified adrenal MC2R expression and an enhanced p-PKA/PKA ratio, corroborate the existence of an ACTH-dependent pathway of GC synthesis at the early stage of Tc infection." (PMID 31998227, 2019). "The poor signaling shown by the MC2R/PKA pathway after 14 days pi indicates that mediators other than ACTH sustain the late GC synthesis in Tc-infected animals, reinforcing the view that GC synthesis is ACTH-dependent only in the first period of infection, and further becomes ACTH-independent." (PMID 31998227, 2019). "However, this scenario does not occur in the late phase of Tc infection, since the MC2R/PKA pathway was evidently downregulated just after 2 weeks, favoring the lack of response to ACTH even in the presence of hormone basal levels." (PMID 31998227, 2019).
MC2R also shares sentences with these, for which no sentence is quoted: Anxiety (2 papers); diabetic kidney disease (2); melanoma (2); type 2 diabetes (2); adrenal tumors (1); androgen excess (1); carcinoma (1); cholestasis (1); congenital hypopituitarism (1); depression (1); eczema (1); endocrine diseases (1); Failure to thrive (1); familial hypocalciuric hypercalcemia (1); glomerular diseases (1); hereditary leiomyomatosis (1); Hyperinsulinemia (1); Jaundice (1); liver steatosis (1); lymphoblastic leukemia (1); McCune-Albright syndrome (1); metabolic disorders (1); Micropenis (1); mineralocorticoid insufficiency (1); nephrotic syndrome (1); renal cell carcinoma (1); secondary hypertension (1); thyroid disorders (1); urofacial syndrome (1); X-linked AHC (1).
A further 1 disease shares a sentence with MC2R in 1 paper.